PRR22 (proline rich 22)
Synonyms: MGC24975
Tractability: No criterion of Open Targets' tractability assessment is met for any kind of drug.
Gene: Protein-coding gene on chromosome 19 (5,782,960 to 5,784,746, reverse strand). Ensembl gene ENSG00000212123.
Subcellular location (Human Protein Atlas): Nucleoplasm; Cytosol; Vesicles
Genetic constraint (gnomAD): Loss-of-function variants: 6 observed, 8.04 expected, observed/expected ratio (o/e) 0.75, 90% interval 0.41 to 1.46. That is too few expected variants to judge how well the gene tolerates losing a copy. Missense variants: 619 observed, 524.19 expected, observed/expected ratio (o/e) 1.18, 90% interval 1.11 to 1.26. Synonymous variants: 318 observed, 246.84 expected, observed/expected ratio (o/e) 1.29, 90% interval 1.17 to 1.41.
Homologues: Orthologues: chimpanzee PRR22 (98% identical), dog PRR22 (68% identical), mouse Prr22 (57% identical), rat Prr22 (56% identical), guinea pig PRR22 (53% identical).
Diseases named in the same sentence as PRR22 in open-access papers:
PRR22 is named in the same sentence as 2 diseases in open-access papers, as found by Europe PMC text mining. Sharing a sentence is not in itself a finding about the gene and the disease. The quoted sentences say what the papers report.
leukemia (1 paper, 2019). A malignant (clonal) hematologic disorder, involving hematopoietic stem cells and characterized by the presence of primitive or atypical myeloid or lymphoid cells in the bone marrow and the blood. "We also detected the genes CATSPERD, PRR22, RFX2, and MILT1, which have been shown to be associated with leukemia." (PMID 31013791, 2019).
cancer (1 paper, 2019). A tumor composed of atypical neoplastic, often pleomorphic cells that invade other tissues. "Further analysis suggested that modulation of angiogenesis-related genes (including ANGPTL4, FN1, HSPG2, SRPX2, KLK5, L1CAM, Prr22, FOXJ1, IL24, and TRIM54) potentially contributes to anlotinib resistance, as anlotinib is a multi-targeted anti-angiogenesis drug for cancer therapy." (PMID 31572680, 2019).